ADIPOR1 (adiponectin receptor 1)
Diseases named in the same sentence as ADIPOR1 in open-access papers (continued):
Sharing a sentence is not in itself a finding about the gene and the disease.
breast carcinoma (continued). "Previous studies have shown that the ADIPOR1, ADORA1, BTG2 and CD46 genes differ significantly between long-term survivors of breast cancer and deceased patients, both in levels of gene expression and DNA copy numbers." (PMID 20553615, 2010). "Last but not least, a new AdipoR1 agonist has been found to display a potential antitumoral role in pancreatic and breast cancers." (PMID 40227577, 2025). "Last, while our study identified AdipoR1/2 as potential therapeutic targets in breast cancer, we did not perform in vivo validation of their effects." (PMID 37454080, 2023). "This highlights AdipoR1 as a target for novel breast cancer pharmacological therapeutics regardless of estrogen or menopausal status." (PMID 28676553, 2017). "This study describes the direct expression/localization of Ki67, COXs, aromatase, eicosanoids, adipokines and their receptors (Ob-R, AdipoR1 and AdipoR2), β-catenin and α-SMA in breast cancer specimens using immunohistochemistry and correlated with pathological parameters." (PMID 26431176, 2015). "Notably, RNA-Seq analysis revealed that AdipoR1 stimulation upregulated ferroptosis-related genes, DDIT3, HMOX1, and IRE1α, and downregulated proliferation-related genes, estrogen receptor and TROP2, in breast cancer cell lines." (PMID 41888104, 2026). "In the functional analysis, AdipoR1 stimulation using the agonist AdipoRon activated AMPK signaling, suppressed proliferation and migration, and induced apoptosis in both hormone receptor (HR)-positive (MCF7, T47D) and triple-negative (MDA-MB-231, MDA-MB-468) breast cancer cells." (PMID 41888104, 2026). "Interestingly, adiponectin receptors are known to be differently expressed in breast cancer cell lines independent of ERα status, with a higher expression of AdipoR1 in MCF-7, T47D and MDA-MB-231 cells, and a higher level of AdipoR2 in MDA-MB-361 cells." (PMID 37240258, 2023). "Comparison of adipokines and their receptors (AdipoR1, AdipoR2 and Ob-R), COXs, aromatase, F2-isoprostanes, prostaglandin F2α, α-SMA and aromatase in breast tissues adjacent to the tumor and tumor tissues of breast cancer patients on the basis of percent of staining area." (PMID 26431176, 2015). "Comparison of adipokines and their receptors (AdipoR1, AdipoR2 and Ob-R), COXs, F2-isoprostanes and prostaglandin F2α, α-SMA and aromatase in the breast tissues adjacent to the tumor and tumor tissues of breast cancer patients on the basis of staining intensity." (PMID 26431176, 2015). "Therefore, therapies that alter the levels/ratio of these adipokines or act to increase the expression of the AdipoR1 may represent interventions that can alter tumor growth microenvironment, increasing the chance of success in obese breast cancer patients regardless of menopausal status." (PMID 28676553, 2017).
type 2 diabetes (31 papers, 2008 to 2025). "A number of studies have demonstrated that SNPs of ADIPOR1and ADIPOR1 are also associated with type 2 diabetes, metabolic syndrome, and coronary artery disease." (PMID 36527105, 2022). "Decreased serum adiponectin levels in type 2 diabetes has been linked to the onset of mitochondrial dysfunction in diabetic complications by impairing AMPK-SIRT1-PGC-1α signaling via impaired adiponectin receptor 1 (AdipoR1) signaling." (PMID 31920982, 2019). "In type 2 diabetic rats induced by high-fat and high-sugar diets, cardiac hypertrophy and decreased heart function are associated with decreased myocardial AdipoR1 expression and AMPK phosphorylation." (PMID 23349663, 2013). "It has been demonstrated that at least for ADIPOR1, sequence variants in its 3'-region, are significant determinants of cardiovascular risk in type 2 diabetes." (PMID 20178558, 2010). "Changes in the expression of AdipoR1 and AdipoR2 were described in monocytes of type 2 diabetes patients and overweight patients with coronary artery disease." (PMID 36527105, 2022). "Upregulated canonical pathways included those related to adipocytokine, insulin, and type 2 diabetes signaling (e.g., Adipor1, Prkab1, and Acacb)." (PMID 25744495, 2015). "However, few studies have reported simultaneous associations between ADIPOR1 variants and type 2 diabetes (T2D), coronary artery disease (CAD) and T2D with CAD." (PMID 24967709, 2014). "Sixty-four tagging single nucleotide polymorphisms in ADIPOQ, ADIPOR1 and ADIPOR2 were genotyped in two general population cohorts consisting of 2,355 subjects, and one cohort of 967 subjects with type 2 diabetes." (PMID 23351195, 2013). "Variants in ADIPOQ, the gene encoding adiponectin, have been shown to influence serum adiponectin concentration, and along with variants in the adiponectin receptors (ADIPOR1 and ADIPOR2) have been implicated in metabolic syndrome and type 2 diabetes." (PMID 23351195, 2013). "Our previous study showed that the expression of myocardial adipoR1 was significantly decreased in type 2 diabetic rats." (PMID 22873349, 2012). "However, the interaction of AdipoR1 CTF351–362 with IDE has diagnostic potential because mechanistic and drug studies have confirmed an impact of IDE on the insulin response in type 2 diabetes and CVAD." (PMID 33511378, 2020). "Several reports have shown that AdipoR1 mRNA level in skeletal muscle was up-regulated by running exercise in rats and mice, and by cycling, running or swimming exercise in healthy and type 2 diabetes human." (PMID 24324732, 2013). "Advanced investigation should be conducted to demonstrate whether the receptors for adiponectin, such as ADIPOR1 and ADIPOR2, have an impact on the risk of developing type 2 diabetes and CAD in a special race." (PMID 23590551, 2013). "It is unknown whether the expression of adipoR2 and NADPH oxidase subunits in the heart and the expression of adipoR1 in aorta are changed by telmisartane treatment in type 2 diabetic rats." (PMID 22873349, 2012). "This study investigated the effect of telmisartan on the expression of adiponectin receptor 2 (adipoR2) and nicotinamide adenine dinucleotide phosphate (NADPH) oxidase subunits in the heart and the expression of adiponectin receptor 1 (adipoR1) in aorta in type 2 diabetic rats." (PMID 22873349, 2012). "Thus, future studies should more comprehensively evaluate the ADIPOR1 gene, especially with respect to the complex relationship between body weight and type 2 diabetes." (PMID 18854016, 2008). "An in vitro study using AdipoR1 and AdipoR2 siRNAs in HCMs highlighted the same significant role-play assigned to both AdipoR1 and AdipoR2 in exerting cardioprotective effects under the presence of excess HG and PA media, which mimics the condition similar to type 2 diabetes." (PMID 35351872, 2022).
type 2 diabetes (continued). "Patients affected by impaired glucose tolerance and type 2 diabetes showed reduced ADIPOR2 mRNA expression in subcutaneous fat, whereas ADIPOR1 mRNA was higher." (PMID 34438765, 2021). "Adiponectin and its signaling through the receptors AdipoR1 and AdipoR2 rank highly in the ongoing search for the holy grail that might improve insulin sensitivity, modulating inflammatory responses, and regulating energy metabolism in patients with obesity and/or Type 2 Diabetes (T2D)." (PMID 28271029, 2017). "ADIPOR1 and ADIPOR2 are considered promising genes for type 2 diabetes, the metabolic syndrome and its complications, such as cardiovascular disease." (PMID 20178558, 2010). "AdipoRon-induced expression of AMPK, PPARα, PGC-1α, and Nrf2 through both AdipoR1 and AdipoR2 are involved in regulating MCT1/2/4 and may support cellular functions by increasing lactate and ATP levels in the sciatic nerve in type 2 diabetic mice." (PMID 40671105, 2025). "Additionally, the decreased AdipoR1 and AMPK activation led to a reduction in fatty acid oxidation and an increase in fatty acid synthesis, promoting the progression of type 2 diabetes." (PMID 34718329, 2021). "The expression levels of AdipoR1 and AdipoR2 in skeletal muscle, as well as plasma adiponectin concentrations, have been described to be lower in individuals with a family history of type 2 diabetes mellitus (T2DM) than in those with no family history." (PMID 25650072, 2015).
metabolic syndrome (19 papers, 2006 to 2026). A cluster of metabolic risk factors for CARDIOVASCULAR DISEASES and TYPE 2 DIABETES MELLITUS. "This upregulation of PPARγ was caused by the AdipoR1/AMPK signaling pathway, which plays a pivotal role in improving dyslipidemia." (PMID 40332475, 2025). "Because AdipoRon activates AMPK by binding to AdipoR1 in muscle, thereby triggering beneficial effects on the metabolic syndrome, and because AMPK is involved in skeletal muscle remodelling, we explored the activation of this vital kinase." (PMID 31965757, 2020). "Because ApN activates AMPK by binding to AdipoR1 in muscle, thereby triggering beneficial effects on the metabolic syndrome and because AMPK is involved in skeletal muscle remodeling, we explored the AMPK signaling pathway." (PMID 26257862, 2015). "Interestingly, alterations in the signaling of AdipoR1 in a mouse model of metabolic syndrome produces circadian alterations in locomotor activity." (PMID 35937866, 2022). "Increased levels of AdipoR1 would reflect a defective compensatory mechanism to overcome this adiponectin resistance, in agreement with previous studies showing a similar response in animal models with features of the metabolic syndrome." (PMID 22353542, 2012). "Decreased expression of specific ANRIL isoforms is reported to affect expression of ADIPOR1 (adiponectin receptor with a role in fatty acid catabolism and inflammation), VAMP3 (membrane protein with a role in phagocytosis) and C11orf10 (in proximity to genes associated with metabolic syndrome)." (PMID 29227965, 2017). "Mouse mutants lacking either or both AdipoR1 and AdipoR2 are without obvious phenotypes when maintained under normal conditions but develop metabolic syndrome symptoms when challenged with high fat diets." (PMID 27082444, 2016). "We have a shortage that we did not include the effect of metabolic syndrome on AdipoR1 expression." (PMID 29179455, 2017).
Hyperglycemia (16 papers, 2008 to 2025). An increased concentration of glucose in the blood. "TG (rs2275737) ADIPOR1 gene genotype carriers were found to have the highest levels of glycosylated hemoglobin (HbA1), whereas TT (rs2275738) caused stable hyperglycemia." (PMID 35366291, 2022). "The protein hydrolysis cleavage product of Adiponectin, gAD, has a higher binding affinity for adipoR1 and inhibits hyperglycemia-induced apoptosis in HUVEC cells by partially linking to adipoR1." (PMID 39558976, 2024). "Our study provides novel findings about the role of AdipoR1-mediated signaling in hyperglycemia-induced neuropathogenesis." (PMID 26247729, 2015). "We showed that AdipoR1 protects cell damage and synaptic dysfunction in the mouse brain in hyperglycemia." (PMID 26247729, 2015). "AdipoR1 and AdipioR2 can be regulated under physiological and pathophysiological states, such as fasting, insulin, hyperglycemia." (PMID 21912612, 2011). "Adiponectin acts via two receptor isoforms – AdipoR1 and AdipoR2 – that are regulated by hyperglycaemia and hyperinsulinaemia in liver and muscle." (PMID 18353182, 2008). "Finally, AdipoR1 activation protects from cell damage and synaptic dysfunction in the brain during hyperglycemia by regulating the survival, proliferation and differentiation of neural stem cells." (PMID 33653273, 2021). "Moreover, they found the expressions of adipoR1/R2 in ob/ob mice were significantly decreased in skeletal muscle, which exhibited hyperglycemia and hyperinsulinemia, as compared to control mice." (PMID 24683323, 2014). "Additionally, the unique allelic variants of the ADIPOR1 gene related to DM2 were discovered in the Crimean population; the TG rs2275737 genotype was related to high levels of HbA1c and the TT rs2275738 genotype—to hyperglycemia." (PMID 35366291, 2022). "Hence, we suggest that further investigations are necessary to understand the cerebral AdipoR1-mediated signaling in hyperglycemic conditions, because the modulation of AdipoR1 might alleviate hyperglycemia-induced neuropathogenesis." (PMID 26247729, 2015). "Additionally, ADPN alleviated hyperglycemia-induced downregulation of Ki-67 (a cell proliferative marker), an effect that was partially reversed by AdipoR1 knockdown but not AdipoR2 silencing." (PMID 41146365, 2025). "However, in our current study, we could not detect any sign of amelioration of hyperglycemia in the AdipoR1/Akita mice, indicating that β-cell-specific overexpression of AdipoR1 failed to protect pancreatic β-cells from apoptosis." (PMID 29304075, 2018).
Glucose intolerance (13 papers, 2013 to 2025). Glucose intolerance (GI) can be defined as dysglycemia that comprises both prediabetes and diabetes. "Our previous study showed that overexpression of AdipoR1 causes resistance to high fat / high sucrose diet induced-weight gain and glucose intolerance in mice." (PMID 29194451, 2017). "AdipoR1/AdipoR2 double-KO mice present glucose intolerance and hyperinsulinemia, demonstrating the key roles of these receptors in the physiological regulation of glucose metabolism and insulin sensitivity." (PMID 27822289, 2016). "AdipoR2-null mice demonstrated a hindered adiponectin-mediated PPAR-α activation and unlike AdipoR1-deficient mice showed resistance to diet-induced glucose intolerance." (PMID 26064110, 2015). "AdipoRon showed very similar effects to adiponectin in muscle and liver, such as an activation of AMK and PPARα pathways, and ameliorated IR and glucose intolerance in mice fed a high-fat diet, which was completely obliterated in adipoR1 and AdipoR2 double-knockout mice." (PMID 24864249, 2014). "Deletion of AdipoR1 blocked the adiponectin-mediated phosphorylation of AMPK, while AdipoR2 gene deletion increased adiposity and glucose intolerance, presumably due to increased gluconeogenesis." (PMID 26064110, 2015).
retinal degeneration (11 papers, 2015 to 2025). Degeneration of the retina. "The finding will help explore a new therapeutic approach for treating retinal degeneration induced by DHA depletion due to ADIPOR1 deficiency in the future." (PMID 33963174, 2021). "In fact, ADIPOR1 is one of many genes implicated in retinal degeneration." (PMID 35015730, 2022). "The knockout (KO) of the adiponectin receptor 1 (AdipoR1) gene causes retinal degeneration." (PMID 30254279, 2018). "The genetic deletion of the Adipor1 gene blocks the ability to take up and incorporate DHA in the PRC and RPE, resulting in the loss of PRC and retinal degeneration." (PMID 33662383, 2021). "In an effort to better understand the mechanism of AdipoR1 KO induced retinal degeneration, we performed RNA-sequencing analysis in two and three week old animals." (PMID 30254279, 2018). "Subsequent analysis of Mfrprd6 mouse eyes also identified an IRBP increase in these mice prior to retinal degeneration akin to the AdipoR1 KO mice." (PMID 30254279, 2018). "AdipoR1 KO mice showed progressive retinal degeneration with a dramatic reduction of unesterified DHA, DHA‐containing GPLs, and very long‐chain PUFA‐containing GPLs in the retina." (PMID 28833063, 2017). "OCT and histology revealed progressive retinal degeneration in AdipoR1−/− mice between 3 and 33 weeks of age." (PMID 25736573, 2015). "Finally, we assessed biological processes and pathways enriched in rods by the identified DEGs at 3 different stages of retinal degeneration in AdipoR1–/– mice." (PMID 35015730, 2022). "Also, polymorphisms of Adipor1 occur in age-related macular degeneration (AMD) and other forms of retinal degenerations." (PMID 33662383, 2021). "In addition to this discrepancy, it has recently been shown that the AdipoR1 KO developed retinal degeneration while the KO of adiponectin did not5, suggesting that ADIPOR1 can definitively act independently of adiponectin." (PMID 30254279, 2018). "After determining that ADIPOR1 is necessary for the visual system since its absence during development results in retinal degeneration and early-onset blindness, we wondered if ADIPOR1 is also needed post-development in adult animals and whether it is needed in both photoreceptors and the RPE." (PMID 30254279, 2018). "An example of its critical meaning for cell function evolves from the finding that the genetic ablation of adiponectin receptor 1 shuts off the uptake of DHA in PRCs and leads to the death of these cells and to retinal degeneration." (PMID 28615451, 2017). "In the context of retinal degeneration, studies have revealed that while both CTRP9 and adiponectin can bind AdipoR1, the knockout of either gene results in milder retinal phenotypes compared to AdipoR1 knockout mice, with adiponectin-deficient mice exhibiting virtually no retinal abnormalities." (PMID 40668916, 2025). "Subsequent analysis of the Mfrprd6 mouse retina demonstrated that these mice are lacking ADIPOR1 in their RPE layer alone, suggesting that loss of ADIPOR1 drives retinal degeneration in this model." (PMID 30254279, 2018). "For instance, mutant of the AdipoR1 gene in retinal pigment epithelial cells results in the inability to take up and retain the essential fatty acid family member docosahexaenoic acid (DHA, 22:6,n-3), further leading to photoreceptor cell death and retinal degeneration." (PMID 34783654, 2021). "Lastly, we profiled gene expression between AdipoR1 WT, heterozygous (HET), and KO animals and found that the interphotoreceptor retinoid-binding protein (IRBP, aka RBP3) was strongly upregulated in KO eyes prior to retinal degeneration, suggesting retinoid metabolism dysfunction." (PMID 30254279, 2018). "Therefore, the maintenance of a balanced DHA/VLC-PUFA relies on MFRP and ADIPOR1, which safeguard proper attainment and distribution of key lipids from the RPE to the PRC that are necessary to sustain sight and function at the onset of AMD and other retinal degenerations." (PMID 33662383, 2021).
intracerebral hemorrhage (9 papers, 2018 to 2023). A cerebrovascular disorder characterized by bleeding into one or both cerebral hemispheres including the basal ganglia and the cerebral cortex. "Recombinant CTRP9 improved neurological function, reduced brain edema, and alleviated inflammation through the AdipoR1/AMPK pathway after intracerebral hemorrhage." (PMID 37077671, 2023). "AdipoR1 agonists protect the brain against ischemic stroke and intracerebral hemorrhage via inhibiting neuronal apoptosis." (PMID 36380279, 2022). "Astrocytic expression of AdipoR1 has also been observed in a mouse model of intracerebral haemorrhage (ICH)." (PMID 32664663, 2020). "Administration of an agonist of AdipoR1 attenuated neuroinflammation after intracerebral hemorrhage in mice." (PMID 31128596, 2019). "Further evidence for the anti-inflammatory actions of adiponectin in the CNS come from a study showing that CTRP9, an AdipoR1 agonist, attenuates neuroinflammation in a mouse model of intracerebral hemorrhage through a AdipoR1/AMPK/NFκB signaling mechanism." (PMID 30692905, 2018). "Additionally, AMPK dysregulation and metabolic dysfunction are found in neurodegenerative processes, and the activation of the AdipoR1/AMPK pathway by AdipoRon has demonstrated therapeutic benefits in neuroinflammation following intracerebral hemorrhage." (PMID 38257725, 2023). "Moreover, APN ameliorated intracerebral hemorrhage-induced neuroinflammation through the AdipoR1-AMPK pathway." (PMID 35720361, 2022). "Studies have shown that the AdipoR1/AMPK pathway is abnormal in diseases such as diabetic nephropathy and intracerebral hemorrhage, and treatments targeting this pathway have been confirmed to be effective." (PMID 37077671, 2023).